ATF4 (activating transcription factor 4)
Diseases named in the same sentence as ATF4 in open-access papers (continued):
Sharing a sentence is not in itself a finding about the gene and the disease.
cancer (continued). "In invasive bladder cancers, it has been demonstrated that ASS-1 loss promotes cancer cell survival through GCN2 expression, and that administration of ADI-PEG-20 causes apoptosis through GCN2/ATF4 mediated CHOP activation." (PMID 39516654, 2023). "Mutation analysis revealed elevated mutation rates for IDH1, HNF4A, and ATF4 in LGG, UCEC, and SKCM, as well as higher mutation rates for this ferroptosis-cancer co-associated gene." (PMID 37304867, 2023). "There is some evidence suggesting that ATF4 regulates eral metabolites, including amino acids and glucose, which promote cancer development." (PMID 36900220, 2023). "Further characterizing the role of RBBP8 and ATF4 in HCC pathogenesis by various transgenic mouse models will be helpful in developing therapeutics against HCC or other cancer types." (PMID 37591836, 2023). "ATF4 is induced by stress responses such as nutrient deprivation and is frequently deregulated in cancer cells because it allows survival of cells with an excessive nutritional demand through bypassing the stress responses." (PMID 37949226, 2023). "Cancer cells usually have an increased level of the stress-induced transcription protein activating transcription factor 4 (ATF4)." (PMID 36900220, 2023). "Previous studies have demonstrated that ATF4 has a protective role against ferroptosis or amino acid deprivation in cancer cells." (PMID 37260977, 2023). "If ATF4 inhibits cellular division/cell-cycle progression then it is possible that cancer cells expressing high levels of ATF4 have found a way to circumvent this inhibition." (PMID 36825279, 2023). "Under ER stress conditions induced by the application of thapsigargin, the depletion of CHI3L1 induces ER stress through the upregulation of PERK and PERK downstream factors (eIF2α and ATF4) in both normal and cancer cells." (PMID 37215572, 2023). "When these VCP inhibitors are combined with Salubrinal treatment, ATF4 expression is enhanced leading to a greater increase in cancer apoptosis than with VCP inhibition alone." (PMID 37601686, 2023). "Overexpression of ATF4 significantly exacerbated the metastatic capability of rarely metastatic 4TO7‐Luc cancer cells in BALB/c mice." (PMID 36739602, 2023). "Increased glutamate drives system xCT cystine/glutamate antiporter activity in cancer cells, where its transcription is controlled by ATF4." (PMID 37930434, 2023). "ANKRD1 shows increased expression during oxidative stress in bovine GC and DDIT4 (also called REDD1) is a regulator of caspase-2 (via the ATF4-dependent pathway) in human cancer cells." (PMID 36737804, 2023). "It was further demonstrated that mitochondrial dysfunction can enhance the chemoresistance of cancer cells via the GCN2-eIF2α-ATF4-xCT pathway." (PMID 37525297, 2023). "Once the autophagy-stimulator activating transcription factor 4 (ATF4) was shown to be elevated after treating several cancer cell lines with a proteasome antagonist, it was discovered that autophagy had a role in resistance to bortezomib." (PMID 37046991, 2023). "ATF4 promotes stress endurance in cancer cells by regulating the expression of multiple stress response genes." (PMID 37425300, 2023). "Tanshinone IIA can sensitize cancer cells to TRAIL-induced apoptosis by upregulating DR5 or selectively activating PERK/ATF4 and inhibiting STAT3." (PMID 37990309, 2023). "Western blot analysis revealed that MYC and ATF4 were highly expressed in NDCs derived from cytotoxin‐treated cancer cells and tumors derived from cytotoxin‐treated HeLa‐Luc NDCs." (PMID 36739602, 2023). "Deletion of ATF4 in parental cancer cells significantly reduces colony formation and metastasis of NDCs, whereas overexpression of ATF4 activates the nonclassical NF‐κB signaling pathway to promote chemotherapy‐induced metastasis of NDCs." (PMID 36739602, 2023). "With respect to matrix-deprivation, an ATF4-mediated pro-survival role against anoikis is also reported in multiple cancer types." (PMID 37425300, 2023).
cancer (continued). "ATF4 is selectively translated in cancer cells in response to amino acid starvation during the integrated stress response (ISR) via the action of the protein kinase GCN2 (encoded by the Eif2ak4 gene) that senses low cellular amino acid levels." (PMID 37998373, 2023). "Cancer cells respond to glutaminolysis blockade via upregulation of activating transcription factor 4 (ATF4), which increases protein catabolism and re-cycling of amino acids." (PMID 36289851, 2022). "ATF4, a key stress responsive transcription factor, is essential for cancer cells to sustain glutamine metabolism when challenged with these various types of stress." (PMID 35963851, 2022). "When Nrf2 was knocked down in cancer cells treated with CB-839 or menadione, there was a reduction in both the transcript and protein levels of ATF4." (PMID 35963851, 2022). "Some genes played poor-prognostic factors in cancers, for example, ATF4 in ACC, BACH1 in LGG and UVM, and FOSL1 in DLBC and UVM." (PMID 35242279, 2022). "Treatment of human cancer cells with several mitochondrial poisons leads to ATF4-dependent increase in de novo serine biosynthesis." (PMID 35115503, 2022). "To verify if the increase in ATF4 protein expression in EAAm-treated cancer cells resulted from the induction of the ER stress, we first performed immunoblot analysis of eIF2 phosphorylation status in cells treated with the EAAm mixture." (PMID 35367410, 2022). "Decreased ATF4 levels were recently described as a mechanism of acquired resistance to cope with a limited availability of amino acids in cancer cells." (PMID 35030165, 2022). "In particular, MYC and ATF4 have been shown to co-regulate EIF4EBP1 transcription in cancer cells, providing one potential mechanism underlying EIF4EBP1 overexpression in cancer." (PMID 35228525, 2022). "This latter process mimics a starvation-like response, with a fall of the NEAA intracellular levels; the resulting Glu shortage activates ATF4 and ER stress leading to mTORC1 inhibition and cancer cell death." (PMID 35367410, 2022). "Overall, these data show that the EAAm mixture inhibits mTORC1 and activates ATF4 and ER stress exclusively in cancer cells." (PMID 35367410, 2022). "In line with this, ATF4 protein induction in M14 by EAAm was absent in the non-glycolytic M14gal, thus indicating that glycolysis inhibition by the mixture was responsible for ATF4 induction/mTORC1 inhibition and cell death of cancer cells." (PMID 35367410, 2022). "The stress-inducible transcription factor, ATF4, has been suggested to play an essential role in the ability of cancer cells to adapt to multiple challenges, including metabolic stress." (PMID 35963851, 2022). "ATF4 promotes ferroptosis resistance in cancer cells by upregulating SLC7A11 as an adaptive response to cystine deficiency." (PMID 36552652, 2022). "ATF4 has been verified as a critical regulator of nutrient metabolism in many kinds of cancers, and its target genes include SLC1A5 and ASNS." (PMID 35864117, 2022). "Previous studies found that ATF4 expression is important for cancer cell proliferation and survival during nutrient deprivation, including glutamine withdrawal, and consequently numerous metabolic enzymes targeted by ATF4 have been identified." (PMID 35963851, 2022). "We now describe how mTORC2-mediated ATF4 transcription is necessary to replenish ATF4 levels to maintain ATF4 function and enable cancer cells to survive sustained metabolic stress." (PMID 35963851, 2022). "The PEAK/eIF2α/ATF4 signal pathway has dual roles that contribute to cell death or survival in cancer cells depending on the variable conditions of the ER in cancer cells." (PMID 35269802, 2022).
cancer (continued). "A clue to the mechanism for the integrative role of PCK2 in cancer metabolism arises from its transcription regulation by ATF4 under nutrient stress." (PMID 35681299, 2022). "We next set out to identify the signaling mechanisms responsible for increases in ATF4 transcription that cancer cells need to survive metabolic stress." (PMID 35963851, 2022). "In human cancer, ATF4 promotes the transcription of genes involved in stress response, including SLC7A11, to increase tumor angiogenesis and shape blood vessel architecture." (PMID 36552652, 2022). "Previous studies have indicated that ATF4 exerts detrimental effects on cancer progression by triggering aggressive phenotypes of cancer cells and inducing treatment resistance." (PMID 35408440, 2022). "ATF4 promotes the expression of ABCC1 which favors the development of multiple drug resistance in cancer cells by extrusion of chemotherapy drugs." (PMID 35646668, 2022). "ATF4 (activating transcription factor 4) has been reported to modulate glutamine metabolism in different cancer studies." (PMID 34887764, 2021). "Firstly, the PERK-eIF2α-ATF4 signaling pathway is responsible for cancer growth and resistance against curative treatment." (PMID 33514437, 2021). "Secondly, silencing ATF4 significantly inhibits autophagy-dependent cell proliferation in acute myeloid leukemia and other cancer types." (PMID 34976799, 2021). "The high expression of xCT protects cancer cells from oxidative stress and promotes resistance to cancer treatment through the reactive oxygen species(ROS)-activated ATF4–xCT pathway." (PMID 34572286, 2021). "show that cancer cells can tolerate this by inducing ATF4-dependent upregulation of ASS1, allowing de novo arginine synthesis." (PMID 33979616, 2021). "Targeting ATF4-induced autophagy is a new strategy to synergize glutaminolysis-targeting therapies for cancer treatment." (PMID 34373753, 2021). "In K-Ras-driven cancer cells, ATF4 activates the mTORC1 pathway by promoting the transcription of asparagine synthase (ASNS) for apoptosis suppression during glutamine deprivation." (PMID 34373753, 2021). "Nevertheless, current evidence suggests that PERK/ATF4 signaling drives EMT by promoting cancer cell migration and invasion." (PMID 33746610, 2021). "Co-treatment with ICG001 and ATF4, however, significantly inhibited cancer cell invasion (p < 0.05)." (PMID 33628101, 2021). "ATF4 is associated with poor prognosis in PDAC patients, and silencing ATF4 inhibits proliferation, migration, cancer stemness, and gemcitabine resistance." (PMID 33782384, 2021). "Overexpression of ATF4 in A549 cells significantly promoted cancer cell growth and invasion (p < 0.05)." (PMID 33628101, 2021). "The function of ATF4 to promote the activity of Wnt/β-catenin signaling in cancer cells was abolished by treatment with ICG001 (p > 0.05)." (PMID 33628101, 2021). "Matrigel invasion assay shows that ICG001 significantly inhibited cancer cell invasion, whereas ATF4 significantly promoted cancer cell invasion (p < 0.05)." (PMID 33628101, 2021). "The endoplasmic reticulum stress mediator cyclic AMP-dependent transcription factor ATF4 plays an important role in the activation of PCK2 expression upon glucose or glutamine deprivation in cancer cells." (PMID 33540663, 2021). "In multiple mouse embryo fibroblast and human cancer cell lines, the mTORC1-ATF4 pathway stimulated expression of only a subset of the ATF4 target genes induced by the ISR, including genes involved in amino acid uptake, synthesis, and tRNA charging." (PMID 33646118, 2021). "Others have provided evidence of its anti-cancer function 9,14, and Dai proved that ATF4 inhibits the progression of pancreatic cancer." (PMID 33628101, 2021). "The PERK/eIF2α/ATF4/CHOP signaling pathway is a potential therapeutic strategy for sensitizing cancer cells." (PMID 34942984, 2021).
cancer (continued). "SLC7A11 transcript levels were also decreased with both ATF4 knockdown and rapamycin in the PTEN-deficient cancer cell lines LNCaP and PC3, although SLC7A11 expression was relatively more resistant to rapamycin in PC3 cells." (PMID 33646118, 2021). "The results show that ATF4 overexpression significantly promoted cancer cell growth and invasion (p < 0.05)." (PMID 33628101, 2021). "Increasing studies show that activating transcription factor 4 (ATF4) is involved in the development of chemoresistance of many cancers." (PMID 34709767, 2021). "A clue on the mechanism for the integrative role of PEPCK-M in cancer metabolism arises from its transcription regulation by ATF4 under nutrient stress." (PMID 33413684, 2021). "PHGDH is overexpressed in many cancers, either via gene copy-number gain, or transcriptional upregulation mediated via activation of transcription factor 4 (ATF4)." (PMID 33397437, 2021). "ATF4 expression in cancer cells including A549 and LK2 was significantly higher than that in HBE cells, both in the nucleus and cytoplasm (p < 0.05)." (PMID 33628101, 2021). "As an example, CEBPB forms functional heterodimers with ATF4, another transcription factor that protects cancer cells under stress conditions." (PMID 34065488, 2021). "The activating transcription factor (ATF4) is another critical regulator of serine/glycine biosynthesis in different cancer types." (PMID 33801846, 2021). "The function of ATF4 in regulating cancer progression was also found to be related to PERK and CCL2 10,15." (PMID 33628101, 2021). "While nuclear HO-1 has limited enzymatic activity in cancer cells, it has been described as a downstream mediator of the activating transcription factor-4 (ATF-4), controlling cancer cell death and metastasis through anoikis." (PMID 34359970, 2021). "In the current study, our data indicate that ATF4 had a positive role in promoting cancer growth and invasion." (PMID 33628101, 2021). "As Atf3−/− mice, unlike Atf4−/− mice, are developmentally normal, drugging ATF3 would be a better strategy than targeting ATF4 for harnessing ferroptosis to treat human diseases including cancer." (PMID 31273299, 2020). "Multiple studies now support a role for Gcn4 during contexts of high growth, including recent reports on the required role of the mammalian ortholog of Gcn4 (ATF4) in driving cancers." (PMID 33378328, 2020). "The activating transcription factor 4 (ATF4) frequently upregulated in cancer cells, was downregulated in MPV17-silenced cells (Z-score = -2,792; P = 1,38E-14)." (PMID 32155188, 2020). "Magnolol sensitized cancer cells to TRAIL-induced apoptosis through ATF4-dependent DR5 upregulation and proteasome-mediated Mcl-1 and c-FLIP downregulation." (PMID 33050112, 2020). "Recently, the PERK/eIF2alpha/ATF4 axis has been involved in the onset and development of different types of cancer." (PMID 32232004, 2020). "Collectively, we showed that magnolol sensitized cancer cells to TRAIL-induced apoptosis through ATF4-dependent DR5 upregulation, proteasome-mediated Mcl-1 downregulation and lysosome-mediated c-FLIP downregulation." (PMID 33050112, 2020). "Since ATF4 helps cells cope with stress, it plays a central role in the survival of cancer cells, which are exposed to proteotoxic stress, hypoxia, nutrient stress, DNA damage, and oxidative stress." (PMID 32938922, 2020). "The lowest correlation genetic interaction was observed between ATF4 and KEAP1, which is not entirely surprising considering KEAP1 has been reported to negatively regulate ATF4 expression in other cancer models." (PMID 33184288, 2020). "Other studies in several cancers also suggest that the mammalian ortholog of Gcn4, called ATF4, is critical to sustain high growth." (PMID 33378328, 2020). "In this context, the adaptation of these cancer cells to a limited availability of nutrients is facilitated by ATF4, one of the master regulators of the cellular stress response." (PMID 33396270, 2020).
cancer (continued). "We find that DENR•MCTS1 levels correlate with ASNS mRNA levels, a readout for ATF4 activity, across the TCGA pan-cancer set." (PMID 32938922, 2020). "Expression of ATF4 is upregulated in cancers and has been shown to promote cell proliferation, survival, drug resistance, migration, and metastasis." (PMID 31064130, 2019). "It has been reported that knockdown of BiP, ATF6, ATF4, and XBP1s can resensitize cancer cells to chemotherapy." (PMID 30813301, 2019). "Taking together, these results strongly suggest that ISR and ATF4 expression leads to up‐regulation of antioxidant genes to deal with the increased oxidative stress and promote cancer cells survival after paclitaxel treatment." (PMID 31211507, 2019). "ATF4 is often overexpressed in cancer cells and promotes cell proliferation, survival, and drug resistance." (PMID 31461933, 2019). "Downregulation of ATF4 has further been shown to prevent cancer cells from being resistant to anticancer drugs, indicating that ATF4 expression is required for cancer cell survival in response to chemotherapy." (PMID 30719230, 2019). "Recently, it is increasingly clear that growth signals activate the ATF4 pathway, especially in cancer cells." (PMID 30705506, 2019). "Drug discovery aimed at promoting cancer cells to apoptosis through the induction of ATF4 is also underway." (PMID 31461933, 2019). "Using Western blot analysis, it has been demonstrated that ER stress-related proteins, such as p-PERK, p-eIF-2α, and ATF4, were modified in apoptotic cancer cells treated with COM." (PMID 30813301, 2019). "PERK can not only activate its downstream transcription factor, ATF4, to increase cancer cell survival but can also trigger Nrf2, also a transcription factor, to block expression of CHOP, which induces cell death signaling." (PMID 31121863, 2019). "In tumors, ATF4 expression is detected in hypoxic- and nutrient-deprived regions where it promotes metabolic homeostasis and cancer cell survival by transcriptionally regulating amino acid uptake and biosynthesis, autophagy, redox balance and angiogenesis." (PMID 31738790, 2019). "By activating ATF4, research on compounds aimed at killing cancer cells is now being vigorously conducted." (PMID 31461933, 2019). "It has been proven that transcription of many essential pro-tumorigenic genes, involved in cancer metastasis, angiogenesis, and drug resistance, is ATF4-driven." (PMID 31491919, 2019). "This identified ATF4, FOXO1, HIF1A, MAF, MYC, and SREBP1 in FGFR-dependent cancer cells whereas ATF4 and MYC in EGFR-addicted cancer cells, which were required for the transcription of the signature genes in glycolysis or SSP." (PMID 31221965, 2019). "A cooperative effect of tBHQ and Tm on NGF and HO-1 expression was also observed in normal human astrocytes (NHAs), suggesting that ATF4 and Nrf2 cooperation is not limited to cancer cells." (PMID 30959808, 2019). "ATF4 is important for metabolism in T cells undergoing activation and regulates T helper effector functions, making ATF4 a potential target for cancer treatment." (PMID 30978945, 2019). "ATF4 expression was reported to be increased in hypoxic regions and areas with impaired nutrient supply in several cancer types." (PMID 30719230, 2019). "During ER stress, ATF4 is selectively translated to promote the expression of molecules that favor the adaptive survival of cancer cells such as SLC7A11/xCT." (PMID 31519193, 2019). "Because the ATF4 expression is increased in many tumors the ISR signaling pathway is being considered as an attractive target for anti-cancer therapy." (PMID 29420561, 2018). "Specifically, it has been shown that deficiency of ATF4 or NRF2 expression decreases SLC7A11 expression, and similar to SLC7A11 deficiency, improves cancer cell survival under glucose starvation." (PMID 29764521, 2018). "At the molecular level, FK866-resistant cancer cells were found to effectively prevent the activation of the EIF2A/ATF4/CHOP pathway that promotes cell death." (PMID 29541451, 2018).